MB (myoglobin)
Diseases named in the same sentence as MB in open-access papers (continued):
Sharing a sentence is not in itself a finding about the gene and the disease.
rhabdomyolysis (continued). "In the case of usage, it is essential to match the settings such as dialysate and blood flow to the special filters used and objectives defined, for example, choosing a filter for the elimination of myoglobin in severe rhabdomyolysis requires high flow rates." (PMID 34362161, 2021). "As a second step, we reproduced these experiments by replacing uromodulin by myoglobin to mimic rhabdomyolysis." (PMID 34099830, 2021). "Several studies have shown myoglobin and CK concentrations to be associated with the occurrence of AKI in the setting of rhabdomyolysis." (PMID 34559325, 2021). "Creatine kinase (CK) and myoglobin are both established biomarkers to diagnose and monitor rhabdomyolysis severity." (PMID 34559325, 2021). "Blood purification with Cytosorb® during high-flux dialysis led to a significant reduction of myoglobin in patients with severe rhabdomyolysis." (PMID 33509234, 2021). "Though CK and myoglobin peaks relate to the extent of intramuscular content release and, therefore, are surrogate of rhabdomyolysis severity, they occur late in the course of rhabdomyolysis." (PMID 34559325, 2021). "Venom induced rhabdomyolysis and intravascular hemolysis leads to a release of muscle enzymes such as creatine kinase and muscle protein such as myoglobin, free hemoglobin (from red blood cells) in the intravascular circulation." (PMID 33706645, 2021). "Effective elimination of myoglobin by CVVHDF in rhabdomyolysis was first reported by Mikkelsen and Toft." (PMID 33176824, 2020). "The patient was diagnosed with rhabdomyolysis on the basis of fatigue, muscle pain, oliguria, marked increases in CK, and myoglobin." (PMID 32481339, 2020). "Increased serum myoglobin concentration is the basis for early diagnosis of rhabdomyolysis; however, myoglobin concentrations tend to normalize within 6–8 hours following exposure." (PMID 33219647, 2020). "Risk factors of stage 2–3 AKI included the need for mechanical ventilation and the severity of the rhabdomyolysis at admission (i.e., serum phosphate, potassium and myoglobin levels at admission)." (PMID 32124091, 2020). "In the current study, the plasma myoglobin concentration was higher in A60 than in the A30 group, indicating A60 as a stronger rhabdomyolysis case." (PMID 33201908, 2020). "Intracellular materials, including myoglobin, electrolytes, and sarcoplasmic proteins, leak into the systemic circulation following rhabdomyolysis." (PMID 33202867, 2020). "Rhabdomyolysis is a muscular disorder characterized by the leakage of skeletal muscle-cell contents (electrolytes, myoglobin and sarcoplasmic proteins) into circulation." (PMID 32124091, 2020). "Serum creatine phosphokinase levels returned to normal, myoglobin levels decreased, and muscle pain was significantly alleviated after cessation of polymyxin B. We identified this as a case of polymyxin B-induced rhabdomyolysis." (PMID 33120846, 2020). "The main distinguishing factor between the two is the presence of rhabdomyolysis in capture shock syndrome and the resultant myoglobin protein detected in the renal tubules, which is the main cause of the kidney injury." (PMID 31304016, 2019). "The consequence is usually extensive myopathy, characterized by rhabdomyolysis and myoglobin-induced kidney injury, which carries a poor prognosis for many of these animals." (PMID 31304016, 2019). "The raised myoglobin concentrations after physical effort can result from subsequent rhabdomyolysis." (PMID 30657773, 2019). "A case report on a patient with rhabdomyolysis showed a decline in serum myoglobin levels by 50% within 4 hours using high cut-off intermittent hemodialysis, while myoglobin levels even increased using standard high-flux dialysis." (PMID 31026303, 2019). "Muscle cell damage and death (rhabdomyolysis) result in the release of creatine phosphokinase (CK) and myoglobin among other intracellular molecules, while the accumulation of myoglobin in the kidneys can lead to renal failure and death." (PMID 30050433, 2018).
rhabdomyolysis (continued). "These 5 dogs exhibited traditional signs of rhabdomyolysis including muscle cramping, short-strided gaits due to myalgia, and visually red/brown urine (myoglobin pigmenturia)." (PMID 30073172, 2018). "During vigorous repeated physical exercise or muscle injury- related disorder such as rhabdomyolysis produce muscle damage releasing myoglobin into circulation, where myoglobin comes in contact with circulatory glucose and/or fructose." (PMID 29334926, 2018). "Myoglobinuria and deposition of myoglobin in renal tubules are the most significant consequence, leading to acute renal failure in 15–50% of patients with rhabdomyolysis." (PMID 28714586, 2017). "Multi-organ failure and rhabdomyolysis followed, and a biopsy showed presence of myoglobin pigmentation in his kidneys and AKI." (PMID 29287591, 2017). "We treated four traumatic rhabdomyolysis patients with Coupled Plasma Filtration Adsorption (CPFA) in order to remove myoglobin followed by 14 hours of Continuous Veno-Venous Hemofiltration (CVVH)." (PMID 28409035, 2017). "Crush syndrome is the systemic consequence of severe rhabdomyolysis characterized by significantly elevated values of creatinine and urea, with myoglobin present in the urine and hyperkalemia." (PMID 27579205, 2016). "When skeletal muscles disintegrate in RM, massive amounts of myoglobin are released into the circulation, playing a vital role in rhabdomyolysis-induced AKI." (PMID 26987113, 2016). "Because most rhabdomyolysis studies are retrospective and involve small sample sizes, the exact role of myoglobin in the progression of the condition and the levels that lead to renal toxicity in rhabdomyolysis are still unclear." (PMID 23497406, 2013). "Serum CK represents a more reliable marker than blood myoglobin for the diagnosis and assessment of the severity of rhabdomyolysis because it lasts for longer periods than blood myoglobin." (PMID 24004920, 2013). "Our observational study also clearly shows that the biochemical hallmarks of rhabdomyolysis (elevated levels of CK and/or myoglobin) are frequently observed in patients admitted to the ICU." (PMID 23497406, 2013). "Meanwhile, episodes of rhabdomyolysis were supported by the recurrent symptoms as follows: exercise intolerance, hyperCKmia, elevated serum myoglobin, and renal failure." (PMID 24207015, 2013). "CK and sMb (serum myoglobin) and uMb (urinary myoglobin) were studied as markers of rhabdomyolysis and AKI (RIFLE criteria)." (PMID 23497406, 2013). "Approximately 30% individuals with rhabdomyolysis develop acute renal failure because of low renal perfusion or direct toxic effect and/or cast formation of myoglobin." (PMID 21532723, 2009). "Though it is important to make the diagnosis and begin proper treatment at an early stage, the diagnosis of rhabdomyolysis is difficult unless specific enzymes and myoglobin in skeletal muscle are detected by laboratory tests." (PMID 17169154, 2006). "Acute renal failure due to rhabdomyolysis has been widely described and its main pathophysiological mechanisms are renal vasoconstriction, intraluminal cast formation and direct myoglobin toxicity." (PMID 15821814, 2005). "This is an uncommon presentation of rhabdomyolysis and acute kidney injury and demonstrates that acute kidney injury due to rhabdomyolysis can have a delayed presentation, which can be confirmed by kidney biopsy findings of acute tubular injury with myoglobin staining casts." (PMID 41694166, 2026). "Rhabdomyolysis is a clinical syndrome that results from rapid breakdown of damaged skeletal muscle, leading to the release of their intracellular contents – primarily creatine kinase, myoglobin, and electrolytes – into the bloodstream." (PMID 41585502, 2026). "Furthermore, the subgroup analysis revealed that the incidences of CKD were 0.6% (95% CI: 0.1 to 17.1) and 1.4% (95% CI: 0.7 to 2.0) when rhabdomyolysis was diagnosed based on serum CK and/or myoglobin levels and serum CK levels, respectively." (PMID 41146051, 2025).
rhabdomyolysis (continued). "The current study suggests that hemoadsorption is an effective method to rapidly and safely reduce myoglobin levels in severe rhabdomyolysis and may improve kidney function." (PMID 41398626, 2025). "The presence of excessive myoglobin is pathognomonic of rhabdomyolysis; however, quantitative measurement of serum myoglobin may not be available in many healthcare settings." (PMID 40310119, 2025). "The glycerol-mediated rhabdomyolysis rat model is characterized by skeletal muscle breakdown and the release of intracellular components such as myoglobin into the bloodstream, where it contributes to renal tubular injury through filtration, reabsorption, and distal precipitation." (PMID 40305356, 2025). "Hence, while we attribute much of the myoglobin clearance to the combination of CytoSorb hemoadsorption and HCO dialysis, it is possible that the natural course of recovery from rhabdomyolysis also played a role in the observed decline in myoglobin levels." (PMID 39872682, 2025). "Second, alterations in CK and myoglobin levels were found in rats after the administration of cerivastatin or gemfibrozil; however, there is little information on the relationship between the elevation of these biomarkers and rhabdomyolysis." (PMID 40093810, 2025). "In summary, the consistent associations in our cohort between elevated myoglobin, CK, LDH, and AKI, combined with mechanistic plausibility and the supporting case literature, support that cytolytic syndrome and rhabdomyolysis represent an important axis for COVID-19-associated AKI." (PMID 41462971, 2025). "Additionally, rhabdomyolysis itself can contribute to liver failure through the release of massive amounts of myoglobin, which can overwhelm hepatic processing and lead to oxidative stress and hepatocyte injury." (PMID 41246770, 2025). "However, the primary objective in rhabdomyolysis is to achieve high diuresis to prevent tubular obstruction and facilitate myoglobin clearance." (PMID 41034327, 2025). "Although sampling occurred ~12 h after the final exercise bout (potentially missing an earlier transient peak), the stability of myoglobin supports the conclusion that overt muscle damage was minimal, and that prior conditioning conferred effective protection against exercise-induced rhabdomyolysis." (PMID 40407450, 2025). "Some studies suggest that the early initiation of RRT in AKI due to rhabdomyolysis, especially when used in conjunction with a hemoadsorber, may improve outcomes by increasing myoglobin clearance and reducing further tubular precipitation." (PMID 39797358, 2025). "A recent consensus statement of international experts concluded that adjuvant hemoadsorption therapy in severe rhabdomyolysis is both feasible and safe and may be an effective method to reduce elevated circulating levels of myoglobin." (PMID 41398626, 2025). "In accidents involving electric eels, we recommend in vivo or post-mortem hematological examination to measure cardiac enzymes, as well as the measurement of other clinical data related to rhabdomyolysis, such as blood potassium and phosphorus levels and urine myoglobin levels." (PMID 40638447, 2025). "Integrating hemoadsorption with MCO membranes may help mitigate competition between cytokine and myoglobin clearance, a particularly relevant consideration in viral infection-induced rhabdomyolysis." (PMID 41267038, 2025). "Elevated CK and myoglobin are important bases for diagnosing rhabdomyolysis." (PMID 40587712, 2025). "However, the intervention led to a rapid and significant reduction of the extremely high myoglobin concentration, which is critical in cases of rhabdomyolysis." (PMID 39872682, 2025). "In this study, we evaluated the antioxidant effect of Sn-HSA on ROS induced by myoglobin in kidney cells to assess whether Sn-HSA has the potential to treat rhabdomyolysis-induced AKI." (PMID 38256961, 2024).
rhabdomyolysis (continued). "Early change of the adsorber in patients with severe rhabdomyolysis, especially in patients with very high myoglobin levels, might increase the efficacy." (PMID 38907120, 2024). "Extracorporeal blood purification with CytoSorb has been increasingly used as an adjunctive therapy in several hyperinflammatory critical care conditions, as well as to remove elevated levels of myoglobin or bilirubin in patients with rhabdomyolysis or liver failure." (PMID 39500494, 2024). "Hence, the measurement of serum myoglobin has a low sensitivity for the diagnosis of rhabdomyolysis." (PMID 39130933, 2024). "Currently therapeutic interventions for the management of rhabdomyolysis and associated AKI mostly focus on fluid therapy, urine alkalinisation and diuretic support to improve both tubular flow and pH with attempts to reduce myoglobin precipitation." (PMID 39085790, 2024). "Therefore, future randomized controlled clinical trials are needed to demonstrate the benefit of CS or other devices for myoglobin removal (e.g. EMiC®2) on the outcome of patients with severe rhabdomyolysis." (PMID 38907120, 2024). "While rhabdomyolysis can occur from seizures, more commonly, it is due to osmolar disturbances from fluid shifts (and subsequent muscle rupture), which can lead to acute kidney injury due to tubular injury from myoglobin." (PMID 38993626, 2024). "The current consensus of the HRTF support that adjuvant hemoadsorption therapy in severe rhabdomyolysis is both feasible and safe and may be an effective method to reduce elevated circulating levels of myoglobin." (PMID 39085790, 2024). "In addition to respiratory challenges, the patient developed acute kidney injury secondary to rhabdomyolysis, a condition resulting from muscle breakdown and myoglobin release, which can overwhelm renal clearance." (PMID 39781151, 2024). "Indeed, the most consistent finding in patients with rhabdomyolysis treated with hemoadsorption is the effective reduction in myoglobin levels." (PMID 39085790, 2024). "Another investigation could verify a relevant myoglobin elimination in CVVHD-HCO in rhabdomyolysis, too." (PMID 38486159, 2024). "Six days after the onset of symptoms, the patient developed rhabdomyolysis and liver/kidney damage; levels of creatine kinase (CK; maximum peak: 729,869 U/L) and myoglobin (> 3,000 ng/mL) were extremely high, although the extent of renal damage was relatively mild." (PMID 37972323, 2023). "Due to the short half-life of myoglobin, its peak level occurs earlier than that of CK, and it is cleared from the circulation within 24 h; it can be used as an early sign of muscle damage to help diagnose rhabdomyolysis." (PMID 37835777, 2023). "In addition to this, attention should be paid to AKI which occurs in amphetamines or opioid-intoxicated patients resulting in rhabdomyolysis, high serum myoglobin, and ultimately nephropathy in consumers." (PMID 37822541, 2023). "Rhabdomyolysis is an acute syndrome characterized by skeletal muscle injuries resulting from trauma, inflammation, or ischemia, which leads to the release of breakdown products, including myoglobin." (PMID 38049866, 2023). "Severe rhabdomyolysis leads to the release of myoglobin and CK into the blood." (PMID 37728069, 2023). "AKI often occurs as a complication of rhabdomyolysis due to myoglobin-induced renal toxicity." (PMID 38049866, 2023). "In addition to the release of high load of nephrotoxic molecules (uric acid and myoglobin) in the circulation, rhabdomyolysis and other cell lysis syndrome are also accompanied by severe hyperphosphatemia." (PMID 38057332, 2023). "Induction of AKI by glycerol leads to rhabdomyolysis that manifests by increased creatine phosphokinase and is followed by the accumulation of proteins resulting from muscle cell damage such as myoglobin within the renal tubules (amorphous deposits), renal tubular cell necrosis, and renal edema." (PMID 37396944, 2023).
rhabdomyolysis (continued). "Orthotoluidine on a urine dipstick (UD) can react with heme molecules in myoglobin and cause hemoglobin molecules to turn blue; therefore, the occurrence of rhabdomyolysis manifests as nonerythrocytic urine and UD positivity." (PMID 37835777, 2023). "Moreover, while rhabdomyolysis and elevated serum/urinary myoglobin correlate with AKI occurrence, they also correlate with trauma severity and other renal insults." (PMID 37661277, 2023). "The exposure of the kidney to increased levels of myoglobin leads to the characteristic kidney injury seen in rhabdomyolysis which may progress to acute renal failure." (PMID 37170192, 2023). "A diagnosis of rhabdomyolysis can then be further supported through lab studies demonstrating an elevated serum creatine kinase, more than five times the upper limit of normal (> 975 IU/L), and positive urine myoglobin." (PMID 37170192, 2023). "Second, the deposition of myoglobin and hemoglobin in renal tubules was reported by previous studies, suggesting that rhabdomyolysis and hemolysis may also contribute to AKI in wasp sting patients." (PMID 37700759, 2023). "The early use of extracorporeal myoglobin removal with Cytosorb® after severe rhabdomyolysis might be an option and should be further investigated as a tool to prevent the development of AKI." (PMID 35141180, 2022). "Because hemoglobin and myoglobin are more soluble in an alkaline solution, alkalinization of the urine with bicarbonate and diuresis (to maintain urinary output at 1-2 mL/kg/hr) can be considered as a renal-protective treatment for rhabdomyolysis." (PMID 36447735, 2022). "Severe cases may also lead to renal failure due to rhabdomyolysis and the release of myoglobin into the circulation after cell destruction and alterations in muscle cell membranes." (PMID 36447735, 2022). "The role of extracorporeal removal of myoglobin in the treatment of rhabdomyolysis-associated severe AKI is not yet fully established." (PMID 35340002, 2022). "Furthermore, infectious rhabdomyolysis is reported to have a poorer prognosis (such as incidence of acute kidney failure) than rhabdomyolysis secondary to exercise events, though peak CK and myoglobin levels are lower in the former." (PMID 36567691, 2022). "Novel MCO membrane might represent the optimal mode of treatment of severe rhabdomyolysis-associated AKI, as it allows for efficient removal of myoglobin, avoids albumin supplementation and is associated with lower costs." (PMID 35340002, 2022). "The pronounced catabolism phenotype stands is characterized by meaningfully elevated myoglobin, which is linked to myalgia and extremely negative rhabdomyolysis, closely related to the intensity and duration of physical activity." (PMID 36287773, 2022). "Thus, his acute renal failure was attributed to myoglobin cast nephropathy in the setting of COVID-19-mediated rhabdomyolysis." (PMID 36578087, 2022). "Exertional rhabdomyolysis is a pathophysiological condition where musculoskeletal cell damage occurs due to intense or excessive exercise indicated by increased creatine kinase or myoglobin levels entering the blood via damaged cell membranes." (PMID 35409969, 2022). "The role of extracorporeal myoglobin removal in the treatment of rhabdomyolysis-associated severe acute kidney injury (AKI) is not yet fully established." (PMID 35340002, 2022). "This reduction in GFR (was second highest of the cohort) did not appear to reflect changes associated with training, or acute exercise-induced rhabdomyolysis, as both the injured athlete and her teammates had very similar changes in post-training CPK and myoglobin." (PMID 34123609, 2021). "However, he continued to have generalized malaise, night sweats, diffuse joint pain, and myalgias and was subsequently noted to have rhabdomyolysis with elevated creatine kinase (CK) and myoglobin levels." (PMID 35103132, 2021).